Y_RNA (Y RNA )
Gene: Miscellaneous RNA gene on chromosome 5 (55,040,847 to 55,040,945, forward strand). Ensembl gene ENSG00000207229.
Homologues: Orthologues: chimpanzee Y_RNA (100% identical), macaque Y_RNA (97% identical). Paralogues in human: Y_RNA (91% identical), RNY3 (90% identical), RNY3P1 (89% identical), Y_RNA (89% identical), Y_RNA (88% identical), Y_RNA (87% identical), RNY3P5 (86% identical), RNY3P7 (86% identical), Y_RNA (86% identical), Y_RNA (85% identical), RNY3P11 (84% identical), RNY3P14 (84% identical), and 95 more.